ENSG00000271793 (novel protein, SYNCRIP-SNX14 readthrough)
Gene: Protein-coding gene on chromosome 6 (85,504,776 to 85,678,733, reverse strand). Ensembl gene ENSG00000271793.
Genetic constraint (gnomAD): Missense variants: 321 observed, 680.82 expected, observed/expected ratio (o/e) 0.47, 90% interval 0.43 to 0.52. Synonymous variants: 234 observed, 223.88 expected, observed/expected ratio (o/e) 1.05, 90% interval 0.94 to 1.16.